P4HA3 (prolyl 4-hydroxylase subunit alpha 3)
Description:
Catalyzes the post-translational formation of 4-hydroxyproline in -Xaa-Pro-Gly-sequences in collagens and other proteins.
Synonyms: C-P4Halpha(III)
Tractability: Antibody: UniProt predicts a signal peptide or a membrane-spanning region.
Gene: Protein-coding gene on chromosome 11 (74,235,801 to 74,311,685, reverse strand). Ensembl gene ENSG00000149380.
Subcellular location: Endoplasmic reticulum lumen
Subcellular location (Human Protein Atlas): Cytosol
Pathways (Reactome):
Disease: Maturation of DENV proteins
Extracellular matrix organization: Collagen biosynthesis and modifying enzymes
Gene Ontology:
Molecular function: procollagen-proline 4-dioxygenase activity; protein binding; iron ion binding; L-ascorbic acid binding; oxidoreductase activity, acting on paired donors, with incorporation or reduction of molecular oxygen
Cellular component: endoplasmic reticulum lumen; procollagen-proline 4-dioxygenase complex; endoplasmic reticulum
Genetic constraint (gnomAD): Loss-of-function variants: 49 observed, 61.04 expected, observed/expected ratio (o/e) 0.8, 90% interval 0.64 to 1.02. The upper end of that interval is the gene's LOEUF score, 1.02, which puts it in group 4 of 6, group 1 being the genes least tolerant of losing a copy. Missense variants: 643 observed, 649.13 expected, observed/expected ratio (o/e) 0.99, 90% interval 0.93 to 1.06. Synonymous variants: 248 observed, 249.22 expected, observed/expected ratio (o/e) 1, 90% interval 0.9 to 1.11.
Homologues: Orthologues: chimpanzee P4HA3 (100% identical), dog P4HA3 (93% identical), guinea pig P4HA3 (91% identical), pig P4HA3 (91% identical), macaque P4HA3 (91% identical), mouse P4ha3 (90% identical), rabbit P4HA3 (85% identical), rat P4ha3 (82% identical), tropical clawed frog p4ha3 (65% identical), zebrafish p4ha3 (57% identical), Drosophila melanogaster PH4alphaEFB (38% identical), Caenorhabditis elegans phy-2 (36% identical), and 29 more. Paralogues in human: P4HA2 (36% identical), P4HA1 (35% identical), P4HTM (17% identical).
Diseases named in the same sentence as P4HA3 in open-access papers:
P4HA3 is named in the same sentence as 51 diseases in open-access papers, as found by Europe PMC text mining. Sharing a sentence is not in itself a finding about the gene and the disease. The quoted sentences say what the papers report.
breast cancer (13 papers, 2016 to 2025). A primary or metastatic malignant neoplasm involving the breast. "More importantly, we also explored the association between P4HA3 depleted and cancer immunotherapy in breast cancer in vivo experiment." (PMID 39504328, 2024). "A recent research relying on the bioinformatic analysis and TCGA database found that up-regulation of P4HA3 was highly linked to genes responding to ECM generation in breast cancer, and higher expression of P4HA3 is relevant to worse prognosis." (PMID 37957566, 2023). "Another study based on the bioinformatic analysis in The Cancer Genome Atlas (TCGA) found that P4HA3 upregulation is highly correlated with genes representing ECM production in breast cancer, and higher P4HA3 expression is associated with a worse prognosis." (PMID 31627190, 2019). "It would be logical that P4HA3 deficiency enhanced susceptibility to ICB therapy for breast cancer." (PMID 39504328, 2024). "Specifically, P4HA2 regulates collagen deposition in breast cancer, and P4HA3 induces TGF‐β/Smad signaling activation to facilitate CRC cell growth and metastasis." (PMID 39764560, 2025). "Specifically, the upregulation of DYNLT3 and P4HA3 as well as the downregulation of ALX4 during aging promote breast cancer progression." (PMID 32539762, 2020). "Knockdown of two upregulated genes (DYNLT3 and P4HA3) or overexpression of the downregulated ALX4 significantly reduced breast cancer cell proliferation, migration, and clonogenicity." (PMID 32539762, 2020). "To further substantiate the stroma-specific expression of P4HA3 we microdissected five breast cancer tumors and analyzed the mRNA in the stroma and cancer cell compartments." (PMID 27809802, 2016). "Additionally, we performed the functional role of P4HA3 in breast cancer, colon cancer and lung cancer in vitro." (PMID 39504328, 2024). "With in vitro experiments, we showed that DYNLT3 and P4HA3 promoted breast cancer malignancy." (PMID 32539762, 2020). "Similarly, the P4HA3 gene acts as an oncogene, is significantly upregulated in breast cancer, and its silencing could suppress the aggressive phenotypes of BC cells." (PMID 38612922, 2024). "ECM imaging was completed after staining and documenting tissue distribution of breast cancer driven cell markers, fibroblast activated protein (FAP), alpha smooth muscle actin (αSMA), and prolyl-4-hydroxylase subunit alpha 3 (P4HA3)." (PMID 34503228, 2021). "To test the potential tumor-promoting roles of the two upregulated ABC genes DYNLT3 and P4HA3, we knocked down their expression in the basal-like breast cancer MDA-MB-231 cells and the luminal B breast cancer BT-474 cells." (PMID 32539762, 2020). "P4HA3, which participates in collagen biosynthesis, drives tumor progression in ccRCC and colorectal cancer through the PI3K-AKT-GSK3β axis, conversely, its depletion enhances ICI efficacy in breast cancer." (PMID 41584585, 2025). "P4HA3 is one of the three P4HA isoforms that has been detected with a notably elevated expression in gastric cancer and is correlated with a poor prognosis in breast cancer." (PMID 33981730, 2021). "DYNLT3, P4HA3, and ALX4 play significant roles in breast cancer progression." (PMID 32539762, 2020). "Moreover, knockdown of P4HA3 reduced growth and metastasis whereas overexpression of ALX4 inhibited the growth of xenografted breast cancer cells in mice." (PMID 32539762, 2020). "In addition, a transcriptomics analysis showed that the transcriptome changes in age and breast cancer‐related genes (DYNLT3, P4HA3, and LX4) during aging may contribute to the progression of breast cancer." (PMID 37688399, 2023). "Furthermore, neither ECM metagene-adjusted P4HA1 nor P4HA2 levels were higher in breast cancer than in normal tissue, which also contrasts what was found for P4HA3." (PMID 27809802, 2016).
breast cancer (continued). "The approach was further developed for breast cancer studies comparing imaging mass spectra of peptide peaks between fibroblastic IHC stains (αSMA, FAP, P4HA3) and a control nonstained tissue of breast tumor." (PMID 34503228, 2021).
gastric cancer (7 papers, 2019 to 2024). A primary or metastatic malignant neoplasm involving the stomach. "Highly expressed P4HA3 was associated with poor prognosis in gastric cancer." (PMID 33932142, 2021). "P4HA3 was significantly upregulated in gastric cancer (GC), stomach adenocarcinoma, melanoma and P4HA3 upregulation was involved in the metastasis and prognosis of GC patients." (PMID 39504328, 2024). "In the previous study, P4HA3 was aberrantly expressed in gastric cancer, colon cancer and squamous cell carcinomas." (PMID 39504328, 2024). "It has been reported that in gastric cancer (GC), P4HA3 is significantly upregulated compared to normal tissue and is associated with unfavorable overall survival (OS)." (PMID 37035741, 2023). "Univariate and multivariate Cox regression analysis of the P4HA3 expression and overall survival in gastric cancer patients." (PMID 35846138, 2022).
pituitary adenoma (4 papers, 2019 to 2023). "P4HA3 is located upstream of the PI3K/AKT signaling pathway, and type VI α6 collagen (COL6A6) interacts with P4HA3 to inhibit pituitary adenoma (PA) growth and metastasis by blocking the PI3K/AKT signaling pathway." (PMID 37035741, 2023). "Aprevious study demonstrated that P4HA3 can suppress the growth andmetastasis of pituitary adenoma via blocking PI3K-Akt pathway." (PMID 35976267, 2022). "Long et.al reported that COL6A6 interacted with P4HA3 to suppress the growth and metastasis of pituitary adenoma via blocking the PI3K-Akt pathway." (PMID 35488336, 2022). "Mechanically, COL6A6 interacted with P4HA3 to suppress the growth and metastasis of pituitary adenoma via blocking PI3K-Akt pathway." (PMID 31627190, 2019). "P4HA3 reverses the inhibitory effect of COL6A6 on EMT in pituitary adenoma (PA)." (PMID 37035741, 2023).
colon cancer (3 papers, 2022 to 2024). "Taken together, we confirmed that miR-1266-3p restrained colon cancer cell proliferation and clone formation, and overexpression of P4HA3 alleviated this effect." (PMID 35433237, 2022). "MiR-1266-3p functioned as a tumor suppressor that inhibited growth, metastasis, and EMT in colon cancer via downregulation of P4HA3." (PMID 35433237, 2022). "In summary, P4HA3 reversed miR-1266-3p-mediated inhibiting migration and invasion of colon cancer cell." (PMID 35433237, 2022). "Reduced levels of P4HA3 expression significantly inhibited the EMT process in colon cancer." (PMID 37035741, 2023). "Subsequently, we assayed the effect of miR-1266-3p on the invasive ability of colon cancer cells using BD Matrigel invasion assay and whether P4HA3 could reverse this effect." (PMID 35433237, 2022). "Following an in-depth analysis of the GSE35834 dataset, It could be demonstrated that miR1266-3p expression in colon cancer tissues correlated remarkably negatively to P4HA3 expression (r = −0.79, P < 0.0001)." (PMID 35433237, 2022). "As a result, it was clear that miR-1266-3p inhibited EMT by targeting P4HA3 in colon cancer." (PMID 35433237, 2022). "To verify the effect of miR-1266-3p on the migratory ability of colon cancer cells and whether P4HA3 can reverse this effect, we performed wound scratching assays in SW480 and HT29 cells." (PMID 35433237, 2022). "In conclusion, miR-1266-3p could inhibit growth, metastasis, and EMT in colon cancer by targeting P4HA3." (PMID 35433237, 2022). "Our work also demonstrated that P4HA3 is a direct target gene of miR-1266-3p and that it could reverse the inhibitory effect of miR-1266-3p on colon cancer growth and metastasis." (PMID 35433237, 2022). "Furthermore, miR-1266-3p inhibited the growth and metastasis of colon cancer in vitro as well as in vivo, and this effect could be alleviated by overexpressing P4HA3." (PMID 35433237, 2022). "More importantly, we found that miR-1266-3p could inhibit EMT in colon cancer by targeting P4HA3." (PMID 35433237, 2022). "However, whether P4HA3 can be regulated by miRNAs in cancer, especially in colon cancer, is unclear." (PMID 35433237, 2022). "To further verify whether P4HA3 overexpression affects the effect of miR-1266-3p on the growth ability of colon cancer, we designed three groups in SW480 and HT29 cells, miR-NC+Vector group, miR-1266-3p mimics+Vector group, and miR-1266-3p+P4HA3 group, respectively." (PMID 35433237, 2022). "The biological function of P4HA3 was proved to be involved in EMT, migration and invasion in colon cancer." (PMID 39504328, 2024). "For further confirming correlation between miR-1266-3p and P4HA3, we downloaded the GSE35834 dataset from GEO, and this dataset contained the matched miRNA and gene expression data collected from 78 samples (23 normal tissues adjacent to cancer and 55 colon cancer tissues)." (PMID 35433237, 2022).
cervical cancer (2 papers, 2022 to 2025). A primary or metastatic malignant neoplasm involving the cervix. "Here, we found upregulation of prolyl 4-hydroxylase subunit alpha 3 (P4HA3), an α-subunit of prolyl hydroxylase, in lymphatic metastatic lesions of cervical cancer, which is strongly associated with poor prognosis." (PMID 41381860, 2025).
diabetes mellitus (2 papers, 2022). A metabolic disorder characterized by abnormally high blood sugar levels due to diminished production of insulin or insulin resistance/desensitization. "Our datasuggested that targeting P4HA3 may serve as a potential therapeuticstrategy to ameliorate obesity-associated diabetes." (PMID 35976267, 2022). "P4HA3 was identified among themost profoundly upregulated genes in obese individuals or diabetic individuals,whose functional role in obesity and diabetes remain unknown." (PMID 35976267, 2022).
Insulin resistance (2 papers, 2022 to 2024). Increased resistance towards insulin, that is, diminished effectiveness of insulin in reducing blood glucose levels. "More importantly,increased P4HA3 expression was significantly associated with HOMA-IR(Homeostatic Model Assessment for Insulin Resistance) in obese with T2DMpatients." (PMID 35976267, 2022). "We alsoperformed oral glucose tolerance test (OGTT) and insulin tolerance tests (ITT).The results demonstrated that P4HA3 silencing increased oralglucose tolerance and improved insulin resistance in db/db mice." (PMID 35976267, 2022).
melanoma (2 papers, 2016 to 2024). A malignant, usually aggressive tumor composed of atypical, neoplastic melanocytes. "Detection of methylated P4HA3 in genomic DNA from the peripheral blood of melanoma patients is a sensitive and specific biomarker of metastatic melanoma." (PMID 27461275, 2016). "Ectopic expression of P4HA2 and P4HA3 has opposing effects on melanoma growth, P4HA2 promoting and P4HA3 inhibiting proliferation of melanoma cell lines." (PMID 27461275, 2016). "To seek mechanistic correlates of the proposed differences between P4HA1/P4HA2 and P4HA3, we modulated expression of P4HA2 and P4HA3 in melanoma cell lines using ectopic expression and knock-down." (PMID 27461275, 2016). "Pharmacological inhibition of C-P4H has anti-proliferative effects on melanoma cells irrespective of P4HA3 status and results in dose-dependent G2-M cell cycle block." (PMID 27461275, 2016).
pulmonary fibrosis (2 papers, 2016 to 2021). Chronic progressive interstitial lung disorder characterized by the replacement of the lung tissue by connective tissue, leading to progressive dyspnea, respiratory failure, or right heart failure. "P4HA3 has been suggested to be associated with pulmonary fibrosis, which is a mesenchymal cell-associated disease." (PMID 34168290, 2021). "It is in this context of interest to note that P4HA3 has been identified as an important contributor to TGFβ-mediated pulmonary fibrosis." (PMID 27809802, 2016).
all (1 paper, 2016). "In all cancers P4HA3 was the gene whose expression had the highest correlation coefficient with the ECM metagene." (PMID 27809802, 2016).
B-cell lymphoma (1 paper, 2014). "In addition, methylation-dependent silencing of P4HA3 in B-cell lymphoma cell lines was previously shown to be reversible by DNMTI treatment, and PABPC5 has been associated with premature ovarian failure but a role for either gene in OC has not been previously reported." (PMID 25003579, 2014).
clear cell renal carcinoma (1 paper, 2022). A malignant epithelial neoplasm of the kidney characterized by the presence of lipid-containing clear cells within a vascular network. "P4HA3 is known to be upregulated in clear cell renal carcinoma and patients with higher expression had worse outcomes, indicating a prognostic role for P4HA3." (PMID 35846138, 2022).
esophageal adenocarcinoma (1 paper, 2023). A malignant tumor with glandular differentiation arising predominantly from Barrett mucosa in the lower third of the esophagus. "The mutation type was predominantly Amplification, with the highest mutation frequency of P4HA3 in Esophageal Adenocarcinoma." (PMID 37035741, 2023).
head and neck squamous cell carcinoma (1 paper, 2022). A squamous cell carcinoma that arises from any of the following anatomic sites: lip and oral cavity, nasal cavity, paranasal sinuses, pharynx, larynx, and salivary glands. "Previous research showed that P4HA3 was up-regulated in head and neck squamous cell carcinoma (HNSCC) tissue, and it was demonstrated to promote HNSCC cell proliferation, invasion, and migration in vitro." (PMID 35368700, 2022).
Hepatic steatosis (1 paper, 2022). Steatosis is a term used to denote lipid accumulation within hepatocytes. "In addition, H&Estaining showed that the hepatic steatosis level in the sh-P4HA3 group wassignificantly reduced.Together, these data suggested that P4HA3 silencing improvedhepatic glucose homeostasis and steatosis in db/db mouse model." (PMID 35976267, 2022).
hepatocellular carcinoma (1 paper, 2021). A malignant tumor that arises from hepatocytes. "The developed workflow used in this study was aimed to investigate proteomic acquired stromal analysis of formerly immunohistochemistry stained breast and hepatocellular carcinoma tissue with markers FAP, αSMA, P4HA3 and PTEN." (PMID 34503228, 2021).
human papillomavirus infection (1 paper, 2024). "P4HA3 regulates focal adhesion, human papillomavirus infection, and the PI3K-Akt, TGF-beta, and MAPK signaling pathways." (PMID 38806556, 2024).
lung carcinoma (1 paper, 2021). "We also investigated P4HA3 expression in tumor tissues from the lung cancer dataset in the Cancer Genome Atlas (TCGA) and its relationship to TNM staging." (PMID 34168290, 2021).
metastatic disease (1 paper, 2016). "Further, the frequent methylation of P4HA3 in metastatic melanoma suggests that P4HA3 may have utility as a tissue and serum biomarker of metastatic disease." (PMID 27461275, 2016).
non-small cell lung carcinoma (1 paper, 2023). A group of at least three distinct histological types of lung cancer, including non-small cell squamous cell carcinoma, adenocarcinoma, and large cell carcinoma. "TGF-β stimulation increases P4HA3 expression, which is associated with EMT in non-small cell lung cancer." (PMID 37035741, 2023).
Obesity (1 paper, 2022). Accumulation of substantial excess body fat. "Together, thesefindings suggested that P4HA3 upregulation in adipose tissueswas implicated in the development of obesity and obesity-associated T2DM." (PMID 35976267, 2022). "Then, we evaluated theexpression of P4HA3 in adipocytes and adipose tissue and exploredits effect on obesity and T2DM." (PMID 35976267, 2022). "Therefore,P4HA3 silencing could potentially enhance insulinresistance and reduce obesity in db/db mice." (PMID 35976267, 2022). "However, although the in vivo P4HA3 silencing by intraperitonealinjection with AAV counteracts HFD-induced obesity and improves insulin resistance,we could not conclude whether the effects come directly from its influence inadipose tissues or liver tissues." (PMID 35976267, 2022).
oral squamous cell carcinoma (1 paper, 2024). "The expression of P4HA3 protein was low in both oral squamous cell carcinoma and normal oral mucosa." (PMID 38806556, 2024).
renal cell carcinoma (1 paper, 2023). "A study found that P4HA3 expression is upregulated in patients with renal cell carcinoma (RCC), promoting cancer growth, invasion, and metastasis." (PMID 37035741, 2023).
steatosis (1 paper, 2022). Increased lipid within the cytoplasm of cells. "P4HA3 knockdown could alsosuppress adipocyte differentiation, alleviate the inflammatory cytokine expression,and improve the regulation of hepatic glucose homeostasis and steatosis." (PMID 35976267, 2022).
triple-negative breast carcinoma (1 paper, 2024). An invasive breast carcinoma which is negative for expression of estrogen receptor (ER), progesterone receptor (PR), and human epidermal growth factor receptor 2 (HER2). "Patients derived xenograft (PDX) and subcutaneous transplantation models were utilized to explore the correlation between P4HA3 and immunotherapy response in triple-negative breast cancer (TNBC)." (PMID 39504328, 2024).
uveal melanoma (1 paper, 2023). A melanoma derived from melanocytes of the uveal tract. "Kaplan-Meier survival analysis showed that P4HA3 high expression in BRCA, CESC, COAD, GBM, HNSC, KIRC, kidney renal papillary cell carcinoma (KIRP), LGG, LUSC, OV, READ, STAD, THCA, UCEC, and uveal melanoma (UVM) had a poor prognosis." (PMID 37035741, 2023).